TOMM20 (translocase of outer mitochondrial membrane 20)
Diseases named in the same sentence as TOMM20 in open-access papers (continued):
Sharing a sentence is not in itself a finding about the gene and the disease.
cancer (continued). "When TOMM20 was depleted, PCa cells underwent EMT, acquired the characteristics of cancer stem-like cells, and developed resistance to AR antagonists." (PMID 37563661, 2023). "MCT1 and TOMM20 are found highly expressed in many human cancers, including ADT cancers, and predict for aggressive disease and poor prognosis." (PMID 35814364, 2022). "Evidence has shown that overexpression of TIGAR in carcinoma cells increases the expression of PGC-1α, NRF1, MitoNEET, and Tomm20, which are important markers of mitochondrial biogenesis and OXPHOS32." (PMID 30814486, 2019). "Chromosome 1 carries several amplified genes already reported in cancer such as ADAMTSL4, Histon2H gene family, MUC1 and TOMM20." (PMID 29844869, 2018). "Lactate is then taken up by cancer cells via MCT1, a bidirectional transporter, and transported to mitochondria via a translocase of the outer mitochondrial membrane (TOMM20), leading to the generation of ATP via OXPHOS." (PMID 27213120, 2016). "With further studies corroborating and expanding on our findings, biomarkers such as TOMM20, MCT4 and MCT1 can serve as early prognostic indicators in thyroid tissue samples of patients suspicious for cancer." (PMID 27213120, 2016). "These adaptations were not due to alterations in mitochondrial mass, with only a modest increase in TOMM20 protein upon cancer regardless of temperature (+15%), accompanied by a decreasing trend of Tfam and Ppargc1a." (PMID 40237521, 2025). "Also, we found that drivers of cancer cell migration and invasion, such as p‐STAT3 and N‐cadherin, were upregulated with TOMM20 overexpression and downregulated in TOMM20 knockdown cells." (PMID 39996379, 2025). "TOMM20 has not been described as a prognostic biomarker in ADT cancers, however it is in other cancers." (PMID 35814364, 2022).
infection (12 papers, 2021 to 2026). The state of being infected such as from the introduction of a foreign agent such as serum, vaccine, antigenic substance or organism. "However, unlike mitophagy induced by MFN-2 depletion, which causes complete mitophagy as evidenced by the reduction in TOMM20 staining in MFN-2-depleted cells, EV-D68 infection induces incomplete mitophagy and uses the mitophagosomes for nonlytic viral egress." (PMID 39677747, 2024). "We then stained both mock-infected and infected cells for MAVS and the mitochondrial marker TOMM20 and found that MAVS still localized to the mitochondria, but the morphology of the mitochondria had changed upon infection." (PMID 38400032, 2024). "In contrast, EV-D68 infection of these cells does not reduce TOMM20 staining." (PMID 39677747, 2024). "Of note, we found a discontinuous fluorescence signal of TOMM20 and the colocalization of Ub and IMMT in response to B. pseudomallei infection, indicating that outer mitochondrial membrane (OMM) severing may contribute to a possibility for IMMT exposure and ubiquitination following infection." (PMID 38834545, 2024).
adenocarcinoma (1 paper, 2023). A common cancer characterized by the presence of malignant glandular cells. "The stable depletion of TOMM20 promoted the transdifferentiation of PCa adenocarcinoma cells into NEPC." (PMID 37563661, 2023). "The stable depletion of TOMM20 promoted the transdifferentiation of PCa adenocarcinoma into NEPC and metastasis." (PMID 37563661, 2023).
myopathy (1 paper, 2025). A disease of the muscle in which the muscle fibers do not function properly. "The expression of voltage dependent anion channel 1 (VDAC1), FUN14 domain containing 1 (FUNDC1), and translocase of outer mitochondrial membrane 20 (TOMM20) genes was not affected neither by the WB myopathy nor by the hypoxia exposure of primary myoblasts." (PMID 40034536, 2025).
TOMM20 also shares sentences with these, for which no sentence is quoted: glioma (4 papers); neuroblastoma (4); Alzheimer disease (3); diabetes (3); emphysema (3); glaucoma (2); Hyperglycemia (2); ischemia (2); neurodegenerative disease (2); Obesity (2); viral infection (2); acute kidney injury (1); anaplastic cancer (1); anorexia nervosa (1); asthenozoospermia (1); astrocytoma (1); autoimmune hepatitis (1); bipolar disorder (1); brain tumors (1); Cachexia (1); cardiac diseases (1); cardiac hypertrophy (1); cerebral infarction (1); cholestasis (1); chordoma (1); chronic hepatitis C (1); cognitive deficits (1); colon cancer (1); depression (1); endometrial tumors (1).
A further 27 diseases each share a sentence with TOMM20 in 1 paper.